GPT (glutamic--pyruvic transaminase)
Diseases named in the same sentence as GPT in open-access papers (continued):
Sharing a sentence is not in itself a finding about the gene and the disease.
lymphopenia (206 papers, 2003 to 2026). Reduction in the number of lymphocytes. "With the proposed XGB method, the factors associated with a worse outcome of tocilizumab use in terms of mortality were: baseline situation at the start of tocilizumab treatment requiring IMV, elevated ferritin, LDH and GPT, lymphopenia, and low PAFI values." (PMID 36012968, 2022). "The factors associated with worse outcome of tocilizumab use in terms of hospital stay were: baseline status at the start of tocilizumab treatment requiring IMV or supplemental oxygen, elevated levels of ferritin, GOT, GPT, CRP, LDH, lymphopenia, and low PaFi values." (PMID 36012968, 2022). "The factors associated with a worse outcome of tocilizumab use in terms of hospital stay were: baseline situation at the start of tocilizumab treatment requiring IMV or supplemental oxygen, elevated levels of ferritin, GOT, GPT, CRP, LDH, lymphopenia, and low PAFI values." (PMID 36012968, 2022). "Blood test revealed normal blood count (no lymphopenia or lymphocytosis or eosinophilia), slight increase of procalcitonin serum level (0.14 ng/mL), C‐reactive protein (CRP, 12.1 mg/dL), and liver enzymes (GOT, GPT, LDH, GGT fourfold levels)." (PMID 32986289, 2021).
hepatocellular carcinoma (185 papers, 2004 to 2026). A malignant tumor that arises from hepatocytes. "Glutamic-pyruvic transaminase 1 (GPT1) is an important regulator of hepatocellular carcinoma growth and plays an important role in amino acid and glucose metabolism." (PMID 36278230, 2022). "The results of this study showed that rhHPPCn treatment effectively reduced the levels of MDA, LDH, GPT, and GOT in human hepatoma SMMC7721 cells after CCl4 treatment, and increased the levels of SOD and GSH-PX." (PMID 31333446, 2019). "The results showed that Hepatoma H22-bearing increased the levels of GOT and GPT significantly and the levels of GOT and GPT decreased after being treated with 5-Fu or Brucea javanica oil compared with the negative control group." (PMID 26508976, 2015).
acute kidney injury (158 papers, 2008 to 2026). Sudden and sustained deterioration of the kidney function characterized by decreased glomerular filtration rate, increased serum creatinine or oliguria. "Bilirubin, serum glutamic oxaloacetic transaminase (SGOT) and serum glutamic pyruvic transaminase (SGPT) were evaluated as liver markers whereas urea and creatinine were monitored for renal failure." (PMID 31533701, 2019).
dengue (148 papers, 2005 to 2026). "Severe dengue cases demonstrated significantly elevated serum glutamic oxaloacetic transaminase and serum glutamic pyruvic transaminase levels compared with patients presenting with warning signs (p < 0.001)." (PMID 41583288, 2025). "Serum glutamic pyruvic transaminase (SGPT) levels were likewise significantly higher in the severe dengue group (mean = 1280 ± 1670.08) compared with the warning signs group (mean = 156.11 ± 154.88), with p < 0.001." (PMID 41583288, 2025). "Serum glutamic-oxaloacetic transaminase and serum glutamic-pyruvic transaminase level increases with increase in dengue severity which is indicated by fall in platelet count as they are negatively correlated with each other." (PMID 35251455, 2021). "Serum glutamic-oxaloacetic transaminase was elevated more than serum glutamic-pyruvic transaminase in dengue patients." (PMID 35251455, 2021). "In agreement, hematocrit values and the levels of plasma glutamic-pyruvic transaminase (TGP) were significantly reduced in dengue patients coinfected with HIV when compared to patients infected with dengue virus only." (PMID 31068600, 2019). "Biochemical liver damage markers, such as aspartate aminotransferase (AST), and serum glutamic oxaloacetic transaminase (SGOT), as well as alanine aminotransferase (ALT) and serum glutamic pyruvic transaminase (SGPT) serum levels, are used to evaluate dengue disease severity." (PMID 27593529, 2016). "Serum glutamic-pyruvic transaminase was elevated in 42.4%, 52.4% and 91.7% patients of dengue without warning signs, warning signs and severe dengue respectively." (PMID 35251455, 2021). "Serum glutamic-pyruvic transaminase was elevated in 42.4%, 52.4% and 91.7% of the patients of dengue without warning signs, with warning signs and severe dengue respectively." (PMID 35251455, 2021).
chronic hepatitis (136 papers, 2003 to 2026). An active inflammatory process affecting the liver for more than six months. "Later on, the medication was used intravenously for chronic hepatitis, plummeting serum AST (GOT) and ALT (GPT) levels in patients." (PMID 28848436, 2017).
Acute hepatitis (130 papers, 2009 to 2026). Acute hepatic injury resulting from inflammation typically accompanied by increased serum alanine transaminase activity. "Carbon tetrachloride can damage the liver, and its metabolite trichloromethyl free radical (CCl3•) can cause acute hepatitis and induce the liver to release large amounts of glutamine transaminase (GOT) and glutein transaminase (GPT)." (PMID 31652733, 2019). "This study was performed on 442 pregnant women with clinically suspected acute hepatitis (and was confirmed by ALT/serum glutamic pyruvic transaminase (SGPT) and bilirubin levels) presenting to the out-patient department (OPD) and accident and emergency department of this institute." (PMID 35602792, 2022). "In the CCl4-induced acute hepatitis model, inhibitory effects of HCIF on the release of GOT and GPT into rat serum were similar to or lower than the corresponding effects mediated by silymarin (50 mg/kg BW)." (PMID 23557275, 2013).
Stroke (130 papers, 2016 to 2026). Sudden impairment of blood flow to a part of the brain due to occlusion or rupture of an artery to the brain. "In addition, GPT, WBC, HDL, TG, and fasting glucose were presented as significant components for cardiovascular outcomes including stroke prediction." (PMID 36076235, 2022).
hyperuricemia (120 papers, 2011 to 2026). An abnormally high level of uric acid. "This study found that individuals with hyperuricemia and FL had higher WBC counts, GPT, and GOT levels." (PMID 40422894, 2025).
injury (116 papers, 2012 to 2026). Damage inflicted on the body as the direct or indirect result of an external force, with or without disruption of structural continuity. "The results showed that Cii can inhibit the increases of serum GOT and GPT levels in rats with alcohol-induced liver injury in a dose-dependent manner." (PMID 34221085, 2021). "The results showed that rhHPPCn could reduce serum GPT and GOT levels in mice with CCl4-induced acute liver injury." (PMID 31333446, 2019).
autoimmune hepatitis (107 papers, 2011 to 2026). Hepatitis caused by autoantibodies. "The animal model of T cell-mediated autoimmune hepatitis has shown that CD25lowFoxP3− Tregs can downregulate the alanine aminotransferase (ALT; glutamic-pyruvic transaminase) level in peripheral blood and inhibit the infiltration of inflammatory cells in the liver tissue." (PMID 30473690, 2018).
sarcopenia (96 papers, 2018 to 2026). Progressive decline in muscle mass due to aging which results in decreased functional capacity of muscles. "Children with sarcopenia showed a significantly higher GGT (p = 0.028), higher GPT (p = 0.003), a significantly higher hs-CRP (p = 0.009), and significantly higher diastolic blood pressure (p = 0.046)." (PMID 35012017, 2022).
central obesity (92 papers, 2008 to 2025). "Similarly, a positive correlation was reported for abdominal obesity, ALAT/GPT and GGT in previous studies." (PMID 39081789, 2024).
heart failure (90 papers, 2009 to 2026). Inability of the heart to pump blood at an adequate rate to meet tissue metabolic requirements. "Univariate analysis showed that SGLT2 inhibitor therapy, age, GPT, LDL-C, T-CHO, HDL-C, gout, and HbA1c were significant factors for heart failure." (PMID 35207759, 2022).
malaria (77 papers, 2008 to 2026). Malaria is a serious and sometimes fatal disease caused by a parasite that commonly infects a certain type of mosquito which feeds on humans. "Also, liver and kidney function tests between khat chewer and non-khat chewer malaria patients revealed that the level of liver enzymes (serum GOT and serum GPT) was significantly higher (P<0.001) among khat chewer than among non-khat chewer malaria patients." (PMID 26173100, 2015).
Hypoglycemia (61 papers, 2012 to 2025). A decreased concentration of glucose in the blood. "Given that GPTs are also involved in gluconeogenesis in liver and kidney, GPT inhibitors may cause hypoglycaemia." (PMID 27321283, 2016). "In this study, 10% of the participants had hypoglycemia at the time of admission, total serum bilirubin was raised among 23%, albumin levels were low for age in 21%, while serum glutamic-oxaloacetic transaminase (S. SGOT) and serum glutamic pyruvic transaminase (S. SGPT) levels were raised in 35%." (PMID 36514594, 2022).
renal dysfunction (59 papers, 2015 to 2026). "ML-based models identified non-traditional predictors of renal dysfunction, including GPT, platelet count, INR, BMI, and age." (PMID 40961111, 2025).
kidney damage (58 papers, 2013 to 2026). "GOT and GPT enzyme levels, which indicate liver damage, and creatinine levels, which indicate kidney damage, were not significantly different between the groups." (PMID 29747696, 2018). "Moreover, there was no organ damage that could be caused by systemic blood circulation, which was evidenced by GOT/GPT (liver damage), BUN/creatinine (kidney damage) and LDH (total organ damage)." (PMID 39894864, 2025).
breast cancer (57 papers, 1985 to 2025). A primary or metastatic malignant neoplasm involving the breast. "Plasma levels of glutamic-oxaloacetic transaminase (SGOT) and serum glutamic-pyruvic transaminase (SGPT) in healthy tumor-free mice, untreated mammary tumor mice, and mice treated with incomptine A and doxorubicin." (PMID 40801624, 2025). "Breast cancer patients' baseline serum GPT levels, on the other hand, were considerably greater than controls(P = 0.02)." (PMID 37701507, 2022).
toxicity (57 papers, 2005 to 2025). The degree to which an agent can damage an organism. "Liver toxicity was investigated from changes in SGOT (serum glutamic oxaloacetic transaminase) and SGPT (serum glutamic pyruvic transaminase)." (PMID 36834702, 2023). "Serum parameters, including glutamic pyruvic transaminase, glutamic oxaloacetic transaminase and alkaline phosphatase, showed no signs of liver toxicity (p > 0.05)." (PMID 40397137, 2025). "Furthermore, levels of serum glutamic oxaloacetic transaminase, glutamic pyruvic transaminase, alkaline phosphatase, and bilirubin indicated no signs of liver toxicity, while creatinine levels suggested no renal toxicity (p > 0.05)." (PMID 35681766, 2022).
malnutrition (56 papers, 2006 to 2025). Inadequate nutrition resulting from poor diet, malabsorption, or abnormal nutrient distribution. "Therefore, the lower value of glutamic-pyruvic transaminase may suggest that patients had poor conditions such as malnutrition." (PMID 37833629, 2023). "When animals suffer from various malnutrition, especially when the liver is damaged, serum GOT and GPT activities could increase." (PMID 35928839, 2022).
Splenomegaly (52 papers, 2010 to 2026). Abnormal increased size of the spleen. "Duration of fever >4 days, rising trend of fever, coated tongue, splenomegaly, C-reactive protein (CRP) (>25 mg/L), serum glutamic pyruvic transaminase (SGPT) (>40 IU/L), and absolute eosinopenia were independent predictors of EF in this study." (PMID 40497217, 2025).
pancreatitis (51 papers, 2006 to 2026). Inflammation of the pancreas. "Except for CpG and TpA, in the pancreatitis gene set, GpT was underrepresented, while ApT, GpT, and TpT were underrepresented in the housekeeping gene set." (PMID 36434531, 2022). "CpG, TpA, and GpT are the dinucleotides with the least odds ratio in the set of 26 genes involved in pancreatitis." (PMID 36434531, 2022). "Compared to caerulein-induced pancreatitis, in caerulein + microlithiasis pancreatitis, higher LDH, GPT and ALP levels in serum were observed, but without an impact on pancreatitis severity." (PMID 41830600, 2026).
alcoholic fatty liver disease (47 papers, 2016 to 2025). Lipid infiltration of the hepatic parenchymal cells that is due to alcohol abuse. "As expected, these animals did not display alcoholic fatty liver disease and there was no increase in hepatic triglyceride content or changes in plasma concentrations of transaminases (GPT and GOT) and GGt." (PMID 27662369, 2016).
chronic obstructive pulmonary disease (46 papers, 2014 to 2026). A chronic and progressive lung disorder characterized by the loss of elasticity of the bronchial tree and the air sacs, destruction of the air sacs wall, thickening of the bronchial wall, and mucous accumulation in the bronchial tree. "In the included patients, SGLT2 inhibitor therapy, age, GPT, LDL-C, T-CHO, HDL-C, and gout were significant factors for total cardiac arrhythmia incidence in the univariate analysis." (PMID 35207759, 2022).
alopecia (44 papers, 2005 to 2025). Hair loss usually from the scalp. "The number of patients experiencing GI reactions, increased BUN, increased GPT, alopecia, and pigmentation in the observation group were decreased compared with that in the control group, and the differences, however, were not statistically significant(p>0.05)." (PMID 39092059, 2024). "At the last follow‐up, at the age of 25 years, he was noted to present with total alopecia, mild elevation of serum transaminases (GOT 54 U/L, GPT 46 U/L) and normal results of urine analysis." (PMID 32395412, 2020). "At the last follow‐up, at the age of 36 years, he was noted to present with total alopecia, mild elevation of serum transaminases (GOT 57 U/L, GPT 48 U/L), leukopenia and mild proteinuria (0,89 g/24 hours and 45 mg/dL)." (PMID 32395412, 2020).
congestive heart failure (39 papers, 2013 to 2025). Failure of the heart to pump a sufficient amount of blood to meet the needs of the body tissues, resulting in tissue congestion and edema. "Increased serum level of GPT is often detected in congestive heart failure." (PMID 23951383, 2013).
osteoporosis (37 papers, 2013 to 2026). A condition of reduced bone mass, with decreased cortical thickness and a decrease in the number and size of the trabeculae of cancellous bone (but normal chemical composition), resulting in increased fracture incidence. "There is also a correlation between low GPT levels and increased circulating osteocalcin levels, the latter is observed in conditions which are characterized by loss of bone substance - such as osteoporosis." (PMID 39556216, 2024).
Pruritus (36 papers, 2005 to 2025). Pruritus is an itch or a sensation that makes a person want to scratch. "After further adjustments with anthropometric variables, fasting glucose, total cholesterol, glutamic pyruvic transaminase, uric acid, albumin, WBC count, and hs-CRP, the PCS concentration was still significantly associated with pruritus." (PMID 36983311, 2023). "On the contrary to IS serum levels, in this case, the relationship between pruritus disappeared after adjustments for glutamic pyruvic transaminase and uric acid concentrations." (PMID 36983311, 2023). "The most common side effects observed include pruritus, dermatitis, and erythema at the application site as well as abnormal laboratory changes, such as increased levels of triglycerides and alanine aminotransferase (glutamic pyruvic transaminase)." (PMID 37024987, 2023).
gout (35 papers, 2016 to 2025). A condition characterized by painful swelling of the joints, which is caused by deposition of urate crystals. "Similar to the results for total arrhythmia, SGLT2 inhibitor therapy, age, GPT, LDL-C, T-CHO, HDL-C, and gout were significant factors for AF incidence in the univariate analysis." (PMID 35207759, 2022).
parasitemia (29 papers, 2007 to 2026). "An evident activity of creatinine kinase (CK), glutamate oxaloacetate transaminase (GOT) and glutamate pyruvate transaminase (GPT) was observed during the peak of parasitemia in the SS, TS and A groups." (PMID 39460337, 2024). "Bz treatment alone did not reverse the hepatic damage induced by parasite infection, however, DB766 alone or in combination with Bz produced a decrease of about 69% and 57% in GPT levels when compared to untreated control." (PMID 21814568, 2011).
ischemic stroke (28 papers, 2014 to 2025). A stroke disorder caused by obstruction of blood flow to the brain, due to thrombotic (local blood clot formation) or embolic (due to a blood clot or other material traveling from another site) event. "For ischemic stroke patients, impaired consciousness, elevated TLC, increased ESR, and raised creatinine and SGPT (serum glutamic-pyruvic transaminase) levels within 24 hours of hospitalization were key indicators of 30-day mortality." (PMID 39650949, 2024).
dyslipidaemia (24 papers, 2014 to 2025). "Elevated GOT and GPT in blood reflect liver damage, and increased blood levels of TG, cholesterol, and high-density lipoprotein (HDL) are key features of dyslipidaemia." (PMID 27612024, 2016).
myocarditis (24 papers, 2015 to 2026). Myocarditis is a condition that is characterized by inflammation of the heart muscle (myocardium). "This is evidenced by the nearly baseline levels of CK, GOT and GPT, along with minimal acute myocarditis, observed in vaccinated animals." (PMID 39460337, 2024).
lymphoma (23 papers, 2013 to 2025). A malignant (clonal) proliferation of B- lymphocytes or T- lymphocytes which involves the lymph nodes, bone marrow and/or extranodal sites. "Among all genes, lactate dehydrogenase genes (LDHA and LDHB) were observed to be the most highly expressed (among the entire transcriptome), followed by transaminase genes (GOT1, GOT2, GPT, and GPT2) with log2 median expression > 10, both in lymphoma patients and cell lines." (PMID 39518046, 2024).
myositis (23 papers, 2010 to 2025). "These included age, sex, duration of illness, clinical diagnosis, severity of muscle weakness, laboratory parameters like ESR, creatinine kinase, transaminases (Serum Glutamic Oxaloacetic Transaminase and Serum Glutamic Pyruvic Transaminase), myositis profile and other autoantibodies." (PMID 36210472, 2022).
lung carcinoma (22 papers, 2017 to 2026). "Five of these variants were listed in dbSNP and two variants were identified as somatic variants in lung cancer (FGFR1 p.(Pro702Tyr)) or in a colon carcinoma ((GPT p.(Glu210Cys), COSMIC database;)." (PMID 31212687, 2019).
type 1 diabetes (22 papers, 2012 to 2026). "The present study demonstrates that rats with type 1 diabetes induced by streptozotocin showed elevated levels of cholesterol, HDL, triglycerides, blood glucose, GPT, alkaline phosphatase, and urea and reduced levels of iron and transferrin 30 days following exposure." (PMID 24971142, 2014).
autoimmune disease (13 papers, 2012 to 2025). A disorder resulting from loss of function or tissue destruction of an organ or multiple organs, arising from humoral or cellular immune responses of the individual to their own tissue constituents. "The liver enzyme GPT was significantly more frequently elevated in cases with autoimmune diseases." (PMID 41426992, 2025).
Hypercalcemia (12 papers, 2016 to 2025). An abnormally increased calcium concentration in the blood. "For example, our associations between as CASR and hypercalcemia, GPT and alanine aminotransferease and UGT1A genes and bilirubin levels, were identified in all ways of filtering functionally annotated variation." (PMID 29545597, 2018).